IDO1 (indoleamine 2,3-dioxygenase 1)
Diseases named in the same sentence as IDO1 in open-access papers (continued):
Sharing a sentence is not in itself a finding about the gene and the disease.
cancer (continued). "PD‐L1/2, TIGIT, and IDO1—all included within the 18‐gene TIS, which was developed as a pan‐cancer predictor of response to pembrolizumab —were also found to independently predict improvement in DFS in the ddCTX arm of our analysis." (PMID 37057719, 2023). "An increased expression of both IDO1 and IDO2 has been observed in various types of cancer including an AhR-mediated expression of IDO2 in the human mammary epithelial cell line MCF10A." (PMID 37408267, 2023). "Blocking IDO1/TDO2 inhibited the colony-forming ability only in CR cell models, further demonstrating altered metabolism via the dependence of CR cancer cells on these enzymes for survival." (PMID 37226257, 2023). "IDO and TDO are found to be constitutively overexpressed in a wide variety of tumors, and overexpression of IDO1 and TDO is correlated with poor prognosis for survival in cancer patients." (PMID 37564938, 2023). "For example, indoleamine 2,3-dioxygenase 1 (IDO1), which is the key enzyme that catalyzes the conversion of Trp to Kyn, is overexpressed in some types of cancer and interferon-γ (IFN-γ)-stimulated cells." (PMID 37895133, 2023). "We also used RNA sequencing (RNA-seq) data from the Cancer Genome Atlas Program (TCGA) database and performed gene set enrichment analysis (GSEA) to explore how IDO1 was involved in the development of RILT." (PMID 36824664, 2023). "The novel immunotherapy agents such as inhibitors of PDCD1, TIGHT, IDO1, CD274, CTLA4 and LAG3 were considered had potential survival benefit in several cancers." (PMID 37608927, 2023). "As immune regulatory enzymes, IDO1 and IDO2 have been found to be important targets of AhR to mediate immunosuppression and promote the growth of cancer cells." (PMID 37408267, 2023). "We speculate that while inhibition of IDO1 remains a viable adjuvant therapy for solid tumors, the overlapping effects of IL4i1 must be accounted for, as potentially both enzymes may need to be inhibited at the same time to produce positive effects in cancer therapy." (PMID 37196768, 2023). "By reducing the expression of constitutive IDO1, COX-2 inhibitors can enhance the efficacy of carcinoma immunotherapy strategies." (PMID 37345200, 2023). "Subsequently, the correlation between key pan-carcinoma molecules (including CTLA4, PDCD1LG2, IDO1, and HAVCR2) and CD86 was calculated." (PMID 37064861, 2023). "Within this same study, researchers also demonstrated that across multiple human cancer types, 32% expressed IDO1 alone, 35% expressed TDO alone, and 51% expressed both markers, making a case for dual IDO1/TDO inhibition." (PMID 36031601, 2022). "The results revealed that CD45 was positively correlated with the expression levels of genes characteristic of exhausted T cells across cancers, such as CXCL9, IL10, CD28, IDO1 and CCR4." (PMID 36061172, 2022). "From a screen of commonly used ion transport targeting small molecules, we found cardiac glycosides to be novel inhibitors of the IDO1 pathway in MDA-MB-231 and A549 cancer cells." (PMID 35150740, 2022). "The increased expression of IDO1 and TDO in malignant tumors leads to tryptophan depletion and accumulation of downstream products." (PMID 36185621, 2022). "While CD276, ENTPD1, IDO1, LGALS9, and VSIR were commonly detected in the Stereo‐seq samples, only IDO1 and LGALS9 seemed to have higher and wider expression in the CSCC samples than in the non‐cancer samples." (PMID 35986392, 2022). "The recent determination of the metabolic landscape of cancer cell lines confirms that accumulation and secretion of kynurenine are correlated with IDO (mainly IDO1) and TDO transcriptional expression, with some cancer cell lines expressing both enzymes." (PMID 35681770, 2022). "In the present study, using ex-vivo organoids cultures, we demonstrated a significant synergistic effect in terms of immune-dependent cancer cell death by the combination of MEK-I, anti-PD-L1 and anti-Ido-1 drugs." (PMID 36419183, 2022).
cancer (continued). "Female athymic nude mice were injected with IDO1-positive BxPC-3 and HPAF-II cells and then randomly divided into control and treatment groups a week after the cancer cell injection." (PMID 35997090, 2022). "Here, to our knowledge, we are the first to report that IDO1 inhibition via epacadostat increased migration of NK and CD4+ T cells towards cancer cells." (PMID 35359980, 2022). "ASPN further induced expression of IDO‐1, KYNU, and PAPP‐A in CEFs, leading to cancer cell dissemination, CD8+ T‐cell cytotoxicity, and activation of IGF‐I signaling in cancer cells." (PMID 34379869, 2022). "We further investigated the correlation between IDO1 and TDO2 expressions and T cell infiltration markers in other types of human cancer, ranked by their immunogenicity." (PMID 35780226, 2022). "In the analysis of inhibitory factors of cancer cells in the CIC, the expressions of PD1, PD-L1, PD-L2, and IDO1 were lower in the high estrogen reactivity group in all cohorts." (PMID 35677163, 2022). "Collectively, these data indicate that IDO1 is up-regulated in PDAC tumors and PDAC cancer cells and has an impact on overall patient survival." (PMID 35997090, 2022). "A cancer study in an animal model derived us from understanding the relationship between COX-2 and IDO1." (PMID 35918736, 2022). "To date, a large number of IDO1 inhibitors have been reported, some of them including epacadostat, BMS986205, and indoximod, have advanced into clinical trials for cancer treatment." (PMID 35371054, 2022). "We also demonstrated that TMEM59L expression was negatively linked with the expression of many immune modulators, including PD-L1, IDO1, TIGIT, CTLA-4, and BTLA in various cancers." (PMID 36618425, 2022). "The present analysis found elevated expression of CD47 not only positively correlated with PD1, PD-L1, CTLA4, but also with multiple other immune checkpoints such as IDO1, CD40, CD160, CD86, CD44 across various cancer types." (PMID 35697717, 2022). "We also demonstrate the anti-cancer effect on PDAC using an in vivo xenograft mouse model and provide evidence that the observed anticancer effect is IDO1-mediated." (PMID 35997090, 2022). "Although less frequently expressed than IDO1, TDO2 can also be detected in cancers, particularly brain and hepatic cancers." (PMID 36145311, 2022). "It was observed that the IDO1 inhibitor induced the migration of immune cells toward both HSC-3 cells and cancer cells isolated from HNSCC patients in this microfluidic device." (PMID 36159996, 2022). "Other potential immune checkpoints, such as LAG3, CD96, PDCD1, BTLA, IDO1, and TIGIT, were also enriched in PTPRD/PTPRT mutant cancers." (PMID 36248841, 2022). "The NLG919 (a potent IDO‐1 inhibitor), OXA, and IDO‐1 inhibitors inducing chemo‐/immunotherapy exhibited cancer elimination efficacy." (PMID 34927373, 2022). "By evaluating inhibitory efficacy of 25 candidate compounds (0–500 nM) in cancer cell lines (SGC-7901 and MKN45 cells), dexamethasone and TWS-119 revealed obvious inhibitory effect on PD-L1 and IDO1 in a dose-dependent manner." (PMID 34175886, 2021). "Given the close relationship between KYN metabolites and inflammatory responses, several drugs targeting COX-2, IDO1, IDO2, or TDO2 are already being tested in clinical trials for the treatment of some cancers, some of which have already been completed." (PMID 34943977, 2021). "There are several other examples for the ectopic expression of immune cell genes in cancer, such as CD36, CD70, CD40, CD47, CD172 and IDO1." (PMID 34885093, 2021). "A number of immune checkpoint proteins were shown to be dysregulated in cancers and infectious diseases, including PD-1/PD-L1, CTLA-4, lymphocyte activation 3 (LAG-3), TIM-3, VISTA, and Indoleamine-2,3 dioxygenase 1 (IDO1)." (PMID 34917131, 2021). "Unfortunately, cancer cells can take advantage of checkpoints such as CTLA-4, PD-1, TIGIT and indoleamine 2, 3-dioxygenase 1 (IDO1) to evade the immune response." (PMID 33262461, 2021).
cancer (continued). "In this study, we found that ERV3-2 expression was correlated with IDO-1 expression in most (10/11) of these cancer types, IDO-2 expression in all (11/11) of these cancer types, and TDO-2 expression in only a few (4/11) of these cancer types." (PMID 34367262, 2021). "The published data on the relationship between the expression of several ICs—PD-L1, B7-H3, B7-H4, IDO1, Gal-3 and -9, CEACAM1, CD155, Siglec-15, and the ADAM17 immune response modulator—with the prognosis of cancer tumors, including GC, are analyzed." (PMID 34943606, 2021). "The estimated IDO1 activity in MDA-MB-231 and SK-OV-3 cancer cells were 0.006–0.039 and 3.551–25.874 nmol ʟ-Kyn/min/mg protein, respectively." (PMID 33541164, 2021). "With the discovery of cancer tissue expression IDO1 or TDO or both, IDO1/TDO combined inhibitors have become a study focus." (PMID 35003126, 2021). "Upregulation of indoleamine-2,3-dioxygenase 1 (IDO1) and tryptophan-2,3-dioxygenase 2 (TDO2) by cancer cells result in the tryptophan degradation into kynurenine." (PMID 35250965, 2021). "For instance, it appears that the catalytic activity of IDO-2 is much lower than IDO-1, and IDO2 expression varies according to cancer type." (PMID 34944437, 2021). "Blockade of the immunosuppressive tryptophan catabolism mediated by indoleamine 2,3-dioxygenase 1 (IDO1) and tryptophan 2,3-dioxygenase (TDO) holds enormous promise for sensitising cancer patients to immune checkpoint blockade." (PMID 33708223, 2021). "This suggests that they have the potential to be developed for IDO1- and TDO-related cancer treatment." (PMID 34201791, 2021). "Based on the results that IL4I1 develops a metabolic resistance mechanism against ICB and/or IDO1 by activating AHR, this research provided a new and crucial avenue for cancer therapy." (PMID 33692337, 2021). "About one-third of cancer cell lines harboring high levels of KYN have simultaneous IDO1 and TDO expression, while the others are driven by either IDO1 or TDO." (PMID 33557876, 2021). "A number of cancer cells, including HCC cells, express TDO and/or IDO-1, which catalyze Kyn production." (PMID 34771474, 2021). "We reviewed data on the relationship between PD-L1, B7-H3, B7-H4, IDO1, Galectin-3 and -9, CEACAM1, CD155, Siglec-15 and ADAM17 expression with cancer development in complex with the results of clinical trials on their inhibition." (PMID 34943606, 2021). "The described model of primary human endometrial cells presents an opportunity for investigating biology of endometrium, especially the immune component (IDO1 and RAGE), in normal and cancer cells." (PMID 33922995, 2021). "We treated cancer cells with dexamethasone and TWS-119, and found that dexamethasone can suppress PD-L1 and IDO1 expression in multiple cancer cell lines, including SGC-7901, MKN-45, SMMC-7721, and BxPC3." (PMID 34175886, 2021). "To date, a large number of IDO1 inhibitors have been reported, some of them, including Epacadostat, BMS986205, Indoximod, PF-06840003, etc., have advanced into clinical trials for cancer treatment." (PMID 33883013, 2021). "The results revealed that PDCD1, IDO1, and CTLA4 were significantly upregulated in cluster 3 patients compared with cluster 1 patients in multiple cancer types." (PMID 33627136, 2021). "Another systemic change observed in cancer patients is an altered tryptophan metabolism, primarily mediated by increased tryptophan 2,3-dioxygenase (TDO) and indoleamine 2,3-dioxygenase 1 (IDO1) activities." (PMID 34884980, 2021). "Therefore, the high IDO1 expression is not a single indicator to decide whether to choose IDO1 inhibitors, and the IDO1 activity assessment may also need multiple factors, including the concentrations of Trp and Kyn as well as the Kyn/Trp ratio in human cancers." (PMID 35003126, 2021). "Moreover, targeting IDO2 together with IDO1 may open new options for cancer immunotherapy." (PMID 34201791, 2021).
cancer (continued). "The Trp-catabolic enzymes (TCEs), indoleamine-2,3-dioxygenase 1 and 2 (IDO1 and IDO2) and tryptophan-2,3-dioxygenase (TDO2), which mediate the first step of the kynurenine pathway (KP), are upregulated in diverse cancer entities." (PMID 34646367, 2021). "We found that CD161 was positively correlated with marker genes of exhausted T cells, immune activating genes, and immunosuppressive genes in pan-cancer such as TIGIT, PDCD1, LAG3, CTLA4, STING1, CD96, and IDO1." (PMID 34305920, 2021). "The results revealed that CD161 was positively correlated with marker genes of exhausted T cells, immune activating genes, and immunosuppressive genes in pan-cancer, such as TIGIT, PDCD1, LAG3, CTLA4, STING1, CD96, and IDO1." (PMID 34305920, 2021). "Indoleamine 2,3-dioxygenase 1 (IDO1) is a promising target in immunomodulation of several pathological conditions, especially cancers." (PMID 33804161, 2021). "Despite the development of such molecules is still at an early stage, promising results have been reported, especially for some crucial proteins involved in cancer immunology, such as GAPDH and IDO1." (PMID 33584695, 2020). "Celecoxib also reduced the expression of programmed death-ligand 1 (PD-L1) and indoleamine 2,3-dioxygenase 1 (IDO-1), which are known to suppress antigen-presenting cells and cytotoxic cellular immune effectors in cancer." (PMID 33121001, 2020). "Indoleamine 2,3-dioxygenase-1 (IDO1) and more recently, tryptophan 2,3-dioxygenase (TDO), are tryptophan-catabolizing enzymes with immunoregulatory properties in cancer." (PMID 32776284, 2020). "IDO1 was also correlated with CD8+ T cells, NK CD56dim cells, Th1 cells and macrophages in more than three different cancers." (PMID 32227579, 2020). "Trp breakdown in patients with malignancies is primarily mediated by increased tryptophan 2,3-dioxygenase (TDO) and indoleamine 2,3-dioxygenase 1 (IDO1) activities." (PMID 32153576, 2020). "The results showed that CTLA-4, IDO1, LAG-3, TIGIT and PD1 were specifically increased most in TBNC among different types of cancer." (PMID 32602545, 2020). "We describe the characterization of a novel small molecule IDO1 inhibitor, NTRC 3883-0, in a panel of biochemical and cell-based assays, and various cancer models." (PMID 33584686, 2020). "In the analysis of inhibitory factors of killing of cancer cells in the CIC, the expression of PD1, PD-L1, PD-L2, and IDO1 were the highest in the hot T-cell infiltrated phenotype." (PMID 33396390, 2020). "Finally, the IDO1 silencing could also be a promising option for treating IDO-expressing cancers." (PMID 30708988, 2019). "Bristol-Myers Squibb Corporation reported the other latest IDO1 inhibitor BMS-986205 (ONO-7701, 5), which is in phase I/II clinical trials in combination with nivolumab in patients with advanced cancers." (PMID 30734612, 2019). "The mechanisms involved in these processes include, but are not limited to, IDO-1, ILT3, and ILT4, which represent potentially promising checkpoint inhibitors in cancer immunotherapy." (PMID 30936876, 2019). "Inhibitors of IDO1 and TDO as well as downstream modulators of the KYN pathway and its targets are therefore being developed for cancer immunotherapy and are advancing into clinical trials." (PMID 31612110, 2019). "The important role of accelerated tryptophan catabolism in escaping immune surveillance makes IDO1 and TDO2 prime targets for development of small molecule drugs to augment cancer immunotherapy." (PMID 31795096, 2019). "Our study firstly clarified that the enhancing migratory ability of cancer cells was interdependent between COL12A1 and IDO1." (PMID 31315643, 2019). "Both enzymes are validated targets for cancer immunotherapy but there is a paucity of potent TDO2 and dual IDO1/TDO2 inhibitors." (PMID 31795096, 2019).
cancer (continued). "Indolamine 2,3-dioxygenase 1 (IDO1) and the tryptophan (TRP)-kynurenine pathway were identified as critical mechanisms in cancer immune escape and their inhibition as an approach with promising therapeutic potential." (PMID 31417567, 2019). "The obtained hits were tested in cancer cell lines expressing mainly IDO1 (SKOV3—ovarian), predominantly TDO2 (A172—brain), and both IDO1 and TDO2 (BT549—breast)." (PMID 31795096, 2019). "Therefore, increased IDO1 level could be taken as a reason of immune escape in cancers." (PMID 31315643, 2019). "Among the three different isoforms of dioxygenases, IDO1, IDO2 and TDO, the former has appeared at centre-stage in the cancer field with hundreds of IDO1 inhibitors discovered in the past." (PMID 31096672, 2019). "These immune-related genes include those that are established or promising targets for cancer immunotherapy such as CTLA4, PD1, PD-L1, PD-L2, IDO1, LAG3, and TIGIT." (PMID 30089500, 2018). "The PD1/PDL1 reverse signaling can activate the eIF2α/ATF4 pathway through IDO1 whose inhibitors are actively undergoing clinical trials in combination with anti-PD1 or anti-PDL1 antibodies to treat cancers." (PMID 30305853, 2018). "C) Distribution of IMPACT, IDO1 and TDO2 expression values across all 15,741 non-cancer (GTEX) and cancer (TCGA) samples examined in this study." (PMID 30466445, 2018). "D) Performance of 5 normalisation methods in assessing differential expression (t-statistic) of TDO2, IDO1 and IMPACT in 28 cancer types relative to their corresponding normal tissues." (PMID 30466445, 2018). "CD276, IDO1, and NKG7 in AML diverge from the pan-cancer trends in intercept and slope of expression observed in non “immune” derived tumor types, highlighting the need for AML-specific understanding of the TME." (PMID 30477280, 2018). "Tumoral IDO1 or TDO2 expression was reported to be correlated with a poor prognosis in several types of tumors, which makes IDO1 and TDO2 as interesting targets for cancer immunotherapy." (PMID 27578919, 2016). "The enzymes most proximal to tryptophan, which result in activation of this pathway, are IDO1, IDO2 and TDO2, and all of these enzymes have been shown to be upregulated in a variety of cancers." (PMID 27572319, 2016). "Both IDO1 and – albeit less frequently – TDO are expressed in human tumors and appear to play a role in tumoral immune resistance, which warrants ongoing drug discovery efforts aimed at the clinical development of IDO and TDO inhibitors for cancer therapy." (PMID 25691885, 2015). "With two recent studies demonstrating that TRP metabolism via TDO represents an alternative route to IDO1 activity employed by tumors, there is an interest in pharmacological targeting of TDO for cancer immunotherapy." (PMID 25628622, 2014). "An analysis of IDO1 dysregulation in cancer showed that JAK/STAT and NF-κB signaling are also essential for IDO1 induction in oncogenically transformed skin epithelial cells." (PMID 22654951, 2012). "Finally, we sought to confirm that INCR1 regulates components of the IFNγ-induced JAK/STAT pathway and the resulting expression of immune checkpoints IDO1, CD274, and PDCD1LG2 in human LUAD cells, as shown in other cancer types." (PMID 40449595, 2025). "TDO is structurally distinct from IDO1 and IDO2 and has a unique function in cancer." (PMID 40332338, 2025). "Current evidence indicates that the dual inhibition of IDO1 and TDO surpasses single-target strategies, effectively reducing immunosuppressive KYN metabolites and enhancing antitumor immune responses across various cancers." (PMID 40868271, 2025). "By combining IDO1 inhibition with ICD inducers, it is possible to not only restore immune function but also amplify the antitumor immune response, overcoming immune suppression and enhancing the overall efficacy of cancer immunotherapy." (PMID 40299564, 2025).